TOMM20 (translocase of outer mitochondrial membrane 20)
Description:
Central receptor component of the translocase of the outer membrane of mitochondria (TOM) complex essential for the recognition and translocation of cytosolically synthesized mitochondrial preproteins. Together with TOMM22 functions as the transit peptide receptor at the surface of the mitochondrion outer membrane and facilitates the movement of preproteins into the TOM40 translocation pore. The TOM complex associates with the ion channel VDAC2 and PINK1 kinase at depolarized mitochondria, this interaction stabilizes PINK1 at the outer mitochondrial membrane and triggers downstream mitophagy by the recruitment of the E3 ubiquitin ligase PRKN. Required for the translocation across the mitochondrial outer membrane of cytochrome P450 monooxygenases (By similarity).
Synonyms: KIAA0016; TOM20; MOM19; MAS20
Tractability: Small molecule: a structure with a bound ligand is known. Antibody: UniProt predicts a signal peptide or a membrane-spanning region. PROTAC: UniProt records ubiquitination sites on it; ubiquitination databases record sites on it; its protein half-life has been measured.
Gene: Protein-coding gene on chromosome 1 (235,109,341 to 235,128,846, reverse strand). Ensembl gene ENSG00000173726.
Subcellular location: Mitochondrion outer membrane
Subcellular location (Human Protein Atlas): Mitochondria
Pathways (Reactome):
Autophagy: PINK1-PRKN Mediated Mitophagy
Metabolism of proteins: Ub-specific processing proteases
Protein localization: Mitochondrial protein import
Gene Ontology:
Molecular function: protein binding; protein transmembrane transporter activity
Biological process: protein localization to mitochondrion; protein import into mitochondrial matrix; protein insertion into mitochondrial outer membrane; tRNA import into mitochondrion; intracellular protein transport; protein targeting; response to 3,3',5-triiodo-L-thyronine; response to muscle activity
Cellular component: mitochondria-associated endoplasmic reticulum membrane contact site; mitochondrial outer membrane; mitochondrion; mitochondrial outer membrane translocase complex; sperm midpiece; TOM complex; cell periphery; migrasome; mitochondrial envelope
Genetic constraint (gnomAD): Loss-of-function variants: 6 observed, 12.45 expected, observed/expected ratio (o/e) 0.48, 90% interval 0.26 to 0.95. The upper end of that interval is the gene's LOEUF score, 0.95, which puts it in group 4 of 6, group 1 being the genes least tolerant of losing a copy. Missense variants: 82 observed, 117.32 expected, observed/expected ratio (o/e) 0.7, 90% interval 0.58 to 0.84. Synonymous variants: 42 observed, 43.78 expected, observed/expected ratio (o/e) 0.96, 90% interval 0.75 to 1.24.
Homologues: Orthologues: guinea pig TOMM20 (100% identical), macaque TOMM20 (100% identical), rabbit TOMM20 (100% identical), dog TOMM20 (99% identical), mouse Tomm20 (99% identical), rat Tomm20 (99% identical), zebrafish tomm20b (87% identical), zebrafish tomm20a (85% identical), tropical clawed frog tomm20 (83% identical), pig TOMM20 (77% identical), Drosophila melanogaster Tom20 (54% identical), Drosophila melanogaster tomboy20 (42% identical), and 1 more. Paralogues in human: TOMM20L (43% identical).
Diseases named in the same sentence as TOMM20 in open-access papers:
TOMM20 is named in the same sentence as 96 diseases in open-access papers, as found by Europe PMC text mining. Sharing a sentence is not in itself a finding about the gene and the disease. The quoted sentences say what the papers report.
melanoma (13 papers, 2018 to 2025). A malignant, usually aggressive tumor composed of atypical, neoplastic melanocytes. "Iron-induced ROS production has emerged as another influential factor in the initiation of pyroptosis, and has specific mechanisms involving mitochondrial translocase of outer mitochondrial membrane 20 (TOMM20)-mediated CASP3 activation in melanoma cells." (PMID 39090114, 2024).
breast carcinoma (8 papers, 2015 to 2025). "Additionally, genes with CNV amplification, such as PARP1 and TOMM20, were also found to be upregulated in breast cancer, while genes with CNV deletion, such as PTEN, were downregulated." (PMID 40564403, 2025). "Finally, through in silico studies, we identified specific biomarkers, including TOMM20, NFE2L2, CAT, and ESR2, correlated with poor prognosis in luminal breast cancer." (PMID 39767718, 2024). "In conclusion, our findings indicate that markers including ESR2, TOMM20, NFE2L2, and CAT not only play a role in mitochondrial oxidative stress but may also influence drug response and cancer recurrence, making them promising biomarkers to predict prognosis in luminal breast cancer." (PMID 39767718, 2024).
osteosarcoma (8 papers, 2021 to 2025). A usually aggressive malignant bone-forming mesenchymal neoplasm, predominantly affecting adolescents and young adults. "Among them, FDX1, TOMM20 and NDUFB9 were associated with poor survival of osteosarcoma while COX11, MFN2 and ATP6V1E1 predicted good." (PMID 37405988, 2023). "In this study, a total of six key cuproptosis-mitochondrion genes (FDX1, TOMM20, NDUFB9, COX11, MFN2 and ATP6V1E1) associated with prognosis of osteosarcoma were finally identified." (PMID 37405988, 2023). "A total of six cuproptosis-mitochondrion genes (FDX1, COX11, MFN2, TOMM20, NDUFB9 and ATP6V1E1) were identified to be associated with the prognosis of osteosarcoma." (PMID 37405988, 2023). "In the osteosarcoma tissue, FDX1, TOMM20, and NDUFB9 are all overexpress to promote the development of osteosarcoma." (PMID 38800967, 2024). "The expression of FDX1, COX11, MFN2, TOMM20 and NDUFB9 at mRNA level was elevated in osteosarcoma cells compared with normal osteoblast hFOB1.19." (PMID 37405988, 2023). "However, we are not aware of any study on the immunological aspects of FDX1, TOMM20, NDUFB9, COX11, MFN2 and ATP6V1E1 in osteosarcoma for the time being, which is a direction we need to study subsequently." (PMID 37405988, 2023). "Finally, it was experimentally verified that the expression of FDX1, COX11, MFN2, TOMM20 and NDUFB9 at mRNA levels was elevated in osteosarcoma." (PMID 37405988, 2023).
Parkinson disease (5 papers, 2016 to 2025). A progressive degenerative disorder of the central nervous system characterized by loss of dopamine producing neurons in the substantia nigra and the presence of Lewy bodies in the substantia nigra and locus coeruleus. "In the context of Parkinson’s disease treatment, inhibiting USP30 increases translocase of outer mitochondrial membrane 20 (TOM20) ubiquitination and promotes mitophagy, offering a potential therapeutic strategy for Parkinson’s disease caused by PTEN-induced kinase 1 (PINK1) or Parkin mutations." (PMID 40918504, 2025).
colorectal cancer (4 papers, 2015 to 2023). A primary or metastatic malignant neoplasm that affects the colon or rectum. "Overexpression of TOMM20 has been associated with malignant features in colorectal cancer (CRC) cells, while inhibition of its gene expression has led to significant reductions in cell proliferation, migration and invasion." (PMID 33339392, 2020). "For example, PIM3 is a proto-oncogene that enhances pancreatic cancer growth by modulating tumor vasculogenesis; PTP4A3 can promote cancer metastasis particularly in colorectal cancers; and TOMM20 expression is associated with tumor size in gastric cancer." (PMID 26253570, 2015). "A recent study reported that high expression of TOMM20 is associated with cell cycle dysregulation in colorectal cancer, which leading to increased cell proliferation and aggressiveness of cancer cells, indicating a correlation between TOMM20 and poor prognosis in colorectal cancer." (PMID 37405988, 2023). "The change in TOMM20 could be related to the increase in mitochondrial ATP-coupling as TOMM20 overexpression has shown to affect proliferation of colorectal cancer, impacting ATP production and mito-potential." (PMID 35578327, 2022).
oral cancer (3 papers, 2021 to 2024). "After time course treatments of POMx, the mitochondrial resident protein (TIMM22 and TOMM20) expressions were detected in oral cancer cells." (PMID 34356350, 2021). "For 24 h POMx incubations, the TIMM22 and TOMM20 are almost unchanged in oral cancer cells." (PMID 34356350, 2021). "We found that the Y341A L344A mLIR successfully reinstated autophagic substrate (SQSTM1) levels alongside mitochondrial proteins (TOMM20 and COX4I1) when compared to wild-type CLU, signifying the ineffectiveness of the CLU LIR mutant in eliciting cisplatin-induced mitophagy in oral cancer cells." (PMID 38447939, 2024).
chondrosarcoma (2 papers, 2021 to 2025). A malignant cartilaginous matrix-producing mesenchymal neoplasm arising from the bone and soft tissue. "Previous studies in our laboratory identified that high‐grade human chondrosarcoma tumors have high expression of TOMM20, and overexpression of TOMM20 in the human chondrosarcoma cell lines L2975 and CH2879 increased cell proliferation and tumor growth." (PMID 39996379, 2025). "We wanted to evaluate if drivers of cancer aggressiveness were downregulated with TOMM20 knockdown in chondrosarcoma." (PMID 39996379, 2025). "To recapitulate, the inhibition of TOMM20 in human chondrosarcoma CH2879 reduced the expression of drivers of cancer aggressiveness, cell viability, and OXPHOS, but increased ROS levels." (PMID 39996379, 2025). "Here, we demonstrate that TOMM20 induces OXPHOS under basal conditions, in the presence of lactate, and in the presence of glutamine in fibrosarcoma and chondrosarcoma and that TOMM20 knockdown reduces the OCR in all conditions." (PMID 39996379, 2025). "TOMM20 overexpression in human chondrosarcoma cells induces proliferation and resistance to apoptosis, chemotherapy resistance, and increases tumor growth." (PMID 39996379, 2025). "Conversely, knocking down TOMM20 using CRISPR‐Cas9 reduced cancer aggressiveness in vivo in both chondrosarcoma and fibrosarcoma mouse models." (PMID 39996379, 2025). "In high‐grade human chondrosarcoma tumors, TOMM20 expression is significantly higher than in low‐grade tumors." (PMID 39996379, 2025). "TOMM20 has been studied in human chondrosarcoma cell lines and found to have higher expression in higher grade chondrosarcomas, indicating a role of increased mitochondrial metabolism, glucose and lactose utilization and oxygen consumption." (PMID 34938658, 2021). "Hence, to further explore molecular biological pathways altered due to TOMM20 enrichment, we performed whole transcriptome RNA‐seq with chondrosarcoma L2975‐control and L2975‐TOMM20 overexpressing cells." (PMID 39996379, 2025). "In addition, TOMM20 downregulation using CRISPR‐Cas9 reduced all known BCL2 apoptosis inhibitory proteins in chondrosarcoma (CH2879) and fibrosarcoma (MCA205)." (PMID 39996379, 2025). "Hence, we showed that the expression of TOMM20 can modulate mouse fibrosarcoma and human chondrosarcoma growth." (PMID 39996379, 2025). "Notably, in chondrosarcoma tumors with TOMM20 knockdown, oxygen consumption was decreased, while extracellular acidification rates (ECAR) were elevated, suggesting a metabolic shift away from OXPHOS." (PMID 39996379, 2025). "Previously, our research showed that TOMM20 overexpression increased OXPHOS in chondrosarcoma." (PMID 39996379, 2025). "Here, we studied the effects of TOMM20 overexpression and downregulation on the redox state, mitochondrial oxidative phosphorylation (OXPHOS), and tumor growth using fibrosarcoma and chondrosarcoma models." (PMID 39996379, 2025). "Here, we investigated the role of TOMM20 in the redox state and oxidative stress, as well as its effects on OXPHOS, cell viability, resistance to apoptosis, and tumor growth by studying fibrosarcoma and chondrosarcoma cells with overexpression or downregulation of TOMM20." (PMID 39996379, 2025).
colitis (2 papers, 2025). Inflammation of the colon. "The effects of cedrol on the mitochondrial outer membrane protein TOMM20 in DSS-induced colitis mice were further examined using immunohistochemistry (IHC) of colon sections." (PMID 41552823, 2025). "CKMT1 knockout did not significantly impact the expressions of Nrf1, Ppara, Tfam, Tomm20, or Nfe2l2 during colitis." (PMID 40089459, 2025).
coronary artery diseases (2 papers, 2023 to 2024). "TOMM20 levels can signal changes in mitochondrial function relevant to increased risk of coronary heart disease in diabetic patients, and PTGR2 is involved in the metabolism of prostaglandin E2, which is involved in vasoconstriction." (PMID 39796045, 2024). "We finally identified ATG5, TOMM20, MFN2 transcriptionally differed between MI and stable coronary artery diseases." (PMID 37304955, 2023).
epilepsy (2 papers, 2022 to 2024). A brain disorder characterized by episodes of abnormally increased neuronal discharge resulting in transient episodes of sensory or motor neurological dysfunction, or psychic dysfunction. "Specifically, the regulation of GLS2 mainly reverses mitophagy during the latent period of epilepsy by affecting the expression of PINK1, p62, LC3, and TOMM20, thereby reducing the occurrence of SLEs." (PMID 39404053, 2024). "Our results show that LC3 B level were significantly increased and TOMM20 and TIMM23 were significantly decreased in the epilepsy model, which indicates an enhanced level of mitophagy in our epileptic mice inducing by KA injection." (PMID 36618822, 2022).
leukemia (2 papers, 2016 to 2025). A malignant (clonal) hematologic disorder, involving hematopoietic stem cells and characterized by the presence of primitive or atypical myeloid or lymphoid cells in the bone marrow and the blood. "Therefore, we exposed wild-type and Atg7−/− K562 leukemia cells to 3 Gy of nuclear radiation and observed the reduction of TOMM20 in both cell types in response to irradiation." (PMID 27091640, 2016).
prostate carcinoma (2 papers, 2023 to 2025). A carcinoma that arises from epithelial cells of the prostate gland. "Consistent with the in vitro data, TOMM20 depletion significantly promoted the metastasis of prostate cancer to the abdominal viscera in NOD/SCID mice, and the survival rate of mice was remarkably reduced." (PMID 37563661, 2023). "By analyzing the GEO database(GSE21034 and GSE80609), we compared the mRNA levels of TOMM20 gene between primary prostate cancer (PCa) and the adjacent benign prostate(BP) or hyperplasia(BPH)." (PMID 37563661, 2023). "However, one study indirectly shows that degradation of TOMM20 by androgen receptor antagonists leads to increased ROS production in prostate cancer cells, contributing to drug resistance." (PMID 39996379, 2025).
Sepsis (2 papers, 2023 to 2025). Sepsis is defined as life-threatening organ dysfunction caused by a dysregulated host response to infection. "In contrast, the Sepsis-plus-hypoxia group showed slight increases in LC3 and TOMM20 but less co-localization than the Sepsis group, suggesting a potentially more efficient mitophagic process under combined sepsis and hypoxia conditions." (PMID 41422365, 2025). "Immunofluorescence demonstrated less colocalization of LC3 and TOMM20 in the sepsis-only group than in sepsis-plus-hypoxia mice, suggesting more efficient mitophagy with hypoxemia." (PMID 41422365, 2025). "By 24 h, the Sepsis group began to show increased LC3 and TOMM20 signals with enhanced co-localization, which became more pronounced at 48 h." (PMID 41422365, 2025).
thyroid cancer (2 papers, 2016 to 2023). "The top five most activated KEGG terms involving TOMM20 were spliceosome, RNA degradation, aminoacyl trna biosynthesis, thyroid cancer, and ubiquitin mediated proteolysis." (PMID 37449209, 2023). "Our group previously characterized tumor metabolism in thyroid cancers specifically looking at TOMM20, MCT4 and MCT1." (PMID 27213120, 2016). "We present a review of the current knowledge of metabolism in thyroid cancer, integrating our recent discoveries on the role of transmembrane lactate transporters MCT1 and MCT4, and a translocase of the outer mitochondrial membrane TOMM20." (PMID 27213120, 2016).
adenomyosis (1 paper, 2022). The growth of endometrial tissue inside the muscular wall of the uterine corpus. "The expression levels of STEAP1, GLT8D2, NME5, and TOMM20 were downregulated and showed statistical significance (p < 0.05) in the adenomyosis group compared with those in the control group." (PMID 36685847, 2022). "In this study, the decreased expression of TOMM20 in adenomyosis indicated the dysregulated mitochondrial function, which can lead to the increased oxidative stress." (PMID 36685847, 2022). "The microarray dataset analysis revealed that the expression levels of TMEM97, GLT8D2, NME5, STEAP1, and TOMM20 were significantly downregulated in the endometrium of women with adenomyosis compared with those in the control group (p < 0.05)." (PMID 36685847, 2022). "This study identified STEAP1, TOMM20, GLT8D2, and NME5 as potential biomarkers for adenomyosis." (PMID 36685847, 2022). "In addition, TOMM20 was positively correlated with the resting CD4 memory T-cell and negatively correlated with monocytes and CD8 T-cell in adenomyosis." (PMID 36685847, 2022).
autism (1 paper, 2012). Persistent deficits in social interaction and communication and interaction as well as a markedly restricted repertoire of activity and interest as well as repetitive patterns of behavior. "The expression of DNAJC19, DNM1L, LRPPRC, SLC25A12, SLC25A14, SLC25A24 and TOMM20 were consistently reduced in at least two of the brain regions of autism patients compared to controls." (PMID 23116158, 2012). "The expression of DNAJC19, DNM1L, LRPPRC, SLC25A12, SLC25A14, SLC25A24 and TOMM20 were reduced in at least two of the brain regions of autism patients." (PMID 23116158, 2012).
bone sarcoma (1 paper, 2025). A sarcoma that arises from the bone. "Additionally, TOMM20 is a prognostic biomarker in chordomas, which are a rare type of bone sarcomas, and TOMM20 expression is higher in recurrent and metastatic chordomas compared to primary tumors." (PMID 39996379, 2025).
chronic hepatitis (1 paper, 2020). An active inflammatory process affecting the liver for more than six months. "As a summary, the different levels of LC3, p62, TOMM20 observed in the CHC and AIH cases indicate autophagy initiation in the examined samples of chronic hepatitis of different etiology." (PMID 32124227, 2020).
dengue (1 paper, 2022). "Confocal microscopy of dengue-infected cells further validated the gradual decline in TFAM levels resulting in a decline in the TFAM:TOMM20 ratio during the course of infection." (PMID 36197108, 2022).
endometrial cancer (1 paper, 2020). Primary or metastatic malignant neoplasm involving the endometrium (mucous membrane that lines the endometrial cavity). "To do this we measured cytoplasmic TOMM20 expression in the endometrial cancer biopsies taken at recruitment to the pre-surgical window study compared with tissue harvested at hysterectomy." (PMID 31819173, 2020). "TOMM20 was noted to selectively stain the epithelial endometrial cancer cells and was largely excluded from the adjacent tumour stromal compartment, thus demonstrating a relative increase in mitochondria in epithelial tumour compared with stromal cells." (PMID 31819173, 2020).
fatty liver (1 paper, 2025). "Our immunofluorescence staining images of TOMM20 from dairy cows’ liver suggested that the quantity of mitochondria reduced after fatty liver incidence, but DHA promoted mitochondrial biogenesis." (PMID 41345683, 2025). "Future studies will focus on a deeper mechanistic understanding, particularly the roles of Mfn2 and TOMM20 in the regulation of mitochondrial dynamics and lipid metabolism using siRNA technique, to better understand how DHA alleviates fatty liver incidence." (PMID 41345683, 2025).